POMZP3 (POM121 and ZP3 fusion)
Synonyms: POM-ZP3; POM121
Tractability: PROTAC: ubiquitination databases record sites on it.
Gene: Protein-coding gene on chromosome 7 (76,601,809 to 76,627,288, reverse strand). Ensembl gene ENSG00000146707.
Subcellular location (Human Protein Atlas): Nuclear membrane; Nucleoplasm
Gene Ontology:
Cellular component: non-collagenous component of interstitial matrix
Genetic constraint (gnomAD): Loss-of-function variants: 10 observed, 13.7 expected, observed/expected ratio (o/e) 0.73, 90% interval 0.45 to 1.24. The upper end of that interval is the gene's LOEUF score, 1.24, which puts it in group 5 of 6, group 1 being the genes least tolerant of losing a copy. Missense variants: 152 observed, 197.42 expected, observed/expected ratio (o/e) 0.77, 90% interval 0.67 to 0.88. Synonymous variants: 56 observed, 72.85 expected, observed/expected ratio (o/e) 0.77, 90% interval 0.62 to 0.96.
Homologues: Orthologues: macaque ZP3 (51% identical), chimpanzee POMZP3 (49% identical), pig ZP3 (45% identical), dog ZP3 (43% identical), guinea pig Zp3 (43% identical), rat Zp3 (42% identical), mouse Zp3 (41% identical), rabbit ZP3 (40% identical), tropical clawed frog zp3 (35% identical), zebrafish zp3e (26% identical), zebrafish zp3a.2 (24% identical), zebrafish zp3a.1 (24% identical), and 3 more. Paralogues in human: ZP3 (54% identical).